NRAS (NRAS proto-oncogene, GTPase)
Diseases named in the same sentence as NRAS in open-access papers (continued):
Sharing a sentence is not in itself a finding about the gene and the disease.
serous neoplasm (1 paper, 2024). "Generally, NRAS mutations are rarely seen in HGSC carcinomas but more commonly in borderline or low-grade serous neoplasms, as seen in patient EOC545." (PMID 39101783, 2024).
soft tissue malignant melanoma (1 paper, 2023). "Previous studies have suggested a low incidence of NRAS–BRAF combined mutation, especially in soft tissue malignant melanoma." (PMID 36875110, 2023).
splenic hemangiosarcoma (1 paper, 2023). "However, while NRAS mutations, 89% of which are Q61R/K/H, are frequent in splenic hemangiosarcoma (mutated in 7% [9/129]), NRAS mutations are not detected in non-splenic hemangiosarcoma." (PMID 37414794, 2023).
Stroke (1 paper, 2016). Sudden impairment of blood flow to a part of the brain due to occlusion or rupture of an artery to the brain. "Five were the targetgenes of let-7 (ESM1, VIM, CDK6, NRAS, and KRAS), 3 of which (ESM1, VIM, and CDK6) were correlated with stroke based on published literatures." (PMID 26830013, 2016).
synovitis (1 paper, 2018). Inflammation of a synovial membrane. "Genes such as NRAS, SPHK2, FOS, CXCR4, PLD1, GNAI2, and PLA2G4F were strongly implicated in synovitis of OA." (PMID 29968759, 2018). "In the present study, we found that NRAS played an important role in synovitis in OA." (PMID 29968759, 2018).
systemic mastocytosis (1 paper, 2025). Systemic mastocytosis (SM) comprises a heterogeneous group of rare acquired and chronic hematological malignancies that are related to an abnormal proliferation of mast cells in tissue, including bone marrow, with or without skin involvement. "Other somatic gene alterations implicated in some cases of advanced systemic mastocytosis include mutations in TET2, SRSF2, ASXL1, RUNX1, CBL, JAK2, NRAS, and KRAS." (PMID 41440762, 2025). "Interestingly, NGS analysis did not detect any mutations in all the other KIT exons analyzed nor in other genes previously reported in patients with advanced systemic mastocytosis (TET2, SRSF2, ASXL1, RUNX1, CBL, JAK2, NRAS, and KRAS)." (PMID 41440762, 2025).
testicular cancer (1 paper, 2021). A primary or metastatic malignant neoplasm that affects the testis. "In a previous analysis of molecular alterations of testicular cancer tumors in The Cancer Genome Atlas (TCGA), the authors identified that somatic mutations of three genes—KIT, KRAS, and NRAS—were commonly observed in testicular cancers." (PMID 34819066, 2021).
testicular tumors (1 paper, 2021). "KRAS mutations were present in 10% of testicular tumors, while fewer than 5% of samples contained mutations in NRAS, PIK3CD, and PIK3CA genes." (PMID 34819066, 2021).
tongue cancer (1 paper, 2022). A malignant neoplasm affecting the tongue. "Among them, AC099850.3 is the most co-expressed lncRNA, which is related to six differently expressed mRNAs, namely (CAV1, NRAS, ACSL3, AURKA, EIF2AK4 and RRM2), and its high expression level is closely related to the reduction in the survival rate of patients with tongue cancer." (PMID 35299954, 2022).
tumors of the nasopharynx (1 paper, 2022). "In contrast, KRAS mutations are found more frequently in sinonasal tumors, and NRAS mutations are found chiefly in tumors of the nasopharynx." (PMID 35600380, 2022). "In contrast, KRAS mutations were more frequent in sinonasal tumors, and NRAS mutations were found chiefly in tumors of the nasopharynx." (PMID 35600380, 2022).
ulcer (1 paper, 2025). "Regarding data limitations, the datasets used lacked key information including BRAF/NRAS gene mutation status and contained insufficient ulcer samples, affecting the comprehensiveness of the analysis." (PMID 40547036, 2025).
uterine sarcoma (1 paper, 2020). "Importantly, a small subset of tumors (composed of a case of UUS that harbored a NRAS G13D mutation, a case of uterine sarcoma with LMNA-NTRK1 fusion and a case of UUS without relevant genomic alteration) stood out consistently from the other tumors." (PMID 32933053, 2020).
vitamin D deficiency (1 paper, 2022). A nutritional condition produced by a deficiency of VITAMIN D in the diet, insufficient production of vitamin D in the skin, inadequate absorption of vitamin D from the diet, or abnormal conversion of vitamin D to its bioactive metabolites. "Habitual factors such as the use of sunscreens also affect the absorption of vitamin D by the skin, resulting in vitamin D deficiency, which can increase the occurrence of NRAS mutations in young women." (PMID 34110110, 2022).
tumor (1,152 papers, 1989 to 2026). "The proportion of successfully tested tumours that were NRAS and KIT mutated were 30.8% (1811/5887) and 5.8% (148/2560)." (PMID 41378737, 2026). "This aligns with our findings, where all tumours with Class I mutations harboured co-driving BRAF or NRAS mutations." (PMID 40107205, 2025). "For the Patient 1, the primary tumor showed an NRAS p.Q61K mutation with multiple CNVs including an allelic imbalance of chromosome 7p, 8p, 13q, and 17p, while the metastasis had a BRAF p.V600K mutation and allelic imbalances on different chromosomes." (PMID 39912776, 2025). "Conversely, one patient who was classified as neo-RAS-WT at the time of first-line progression reacquired NRAS A146T mutation, originally detected in primary tumor tissue." (PMID 40227564, 2025). "NRAS mutations are typically associated with higher rates of mitosis and thicker tumours compared to BRAF V600E." (PMID 40447784, 2025). "A link between NRAS mutations and more aggressive tumour features, including a higher chance of metastasis and death, has been suggested." (PMID 40831998, 2025). "A specific analysis of known cancer driver genes revealed NRAS as the most frequently mutated gene (6/8 tumor populations), followed by KMT2D (5/8 tumor populations) and COL5A1 (5/8 tumor populations)." (PMID 40004220, 2025). "Deletion of NRAS or HRAS have shown to cause either a tumor promoting or tumor suppressive effect dependent of the type of cancer." (PMID 40596921, 2025). "Differential effects of oncogenic KRAS and NRAS mutations on proliferation, differentiation, and tumor progression in the colon have been reported in genetically engineered mice." (PMID 40694264, 2025). "FoundationOne next-generation sequencing of the tumor showed mutations in NRAS, CTNNB1, and SMAD4 with microsatellite stability and low tumor mutation burden." (PMID 41120769, 2025). "The significant contribution that KRAS, BRAF, and NRAS mutations predominate in serous borderline precursors suggests a stepwise model for tumor development and reinforces the importance of MAPK signaling in the biology of disease." (PMID 41376748, 2025). "Patient MEL30 was diagnosed with a metastatic cutaneous melanoma wild-type (WT) for BRAF and NRAS genes in its primary tumor but a BRAF V600E mutation was present in a resected lymph node metastasis." (PMID 38898234, 2024). "Our findings are also supported by a previous study on BRAF and NRAS mutation frequencies among primary tumours and their paired metastasis describing a 15% discrepancy in mutational status." (PMID 38127894, 2024). "As for NRAS variants, their prevalence differentiated lgOvCa from all the other tumor groups investigated in our study." (PMID 39456660, 2024). "Consecutive liver sections further confirmed that AR WT induce tumor in NRAS dependent HDT mice, and the AR mutations further accelerated hepatocarcinogenesis as indicated by KI67 staining." (PMID 38182647, 2024). "BRAF V600E and NRAS mutations (NRAS Q61R, NRAS Q61K) were found in tumor tissue in 35.5% (11/31) and 19.4% (6/31) patients, respectively." (PMID 38898234, 2024). "It has been reported in the literature that KRAS mutations were associated with CRC metastasis, NRAS promotes the colonization of the lungs by various tumor types in mouse models." (PMID 39507527, 2024). "Substitution of Q61K results in a constitutively active NRAS protein and is therefore associated with tumor formation." (PMID 39273574, 2024). "Microsatellite instability (MSI) status and KRAS/NRAS/BRAFV600E mutation status were concordant among all multiregional samples from each tumor with CMS heterogeneity." (PMID 38773143, 2024).
tumor (continued). "We found that NRAS mutation correlated with decreased survival and that tumor mutational burden (an estimate of the amount of genetic change within each tumor) correlated with improved responses to immune checkpoint inhibition." (PMID 38611025, 2024). "Another common condition between the two patients was the tumor presence of NRAS mutated at the Q61 site." (PMID 39148899, 2024). "For a given specimen, pathogenic variants of BRAF, EGFR, KRAS, and NRAS were identified and the determined VAFs were correlated with the corresponding tissue tumor cellularity." (PMID 38397405, 2024). "Results indicated a significant, concentration-dependent reduction in tumor-forming potential of cancer cells expressing oncogenic NRAS, KRAS, and HRAS mutations upon treatment with BAY 11-7092." (PMID 38982514, 2024). "This tumor harbored an NRAS codon 61 mutation, which has been associated with a higher rate of metastases compared to other RAS mutations in FTCs." (PMID 39363120, 2024). "Accordingly, NRAS mutations can lead to resistance of tumor cells to a variety of chemotherapeutic agents that damage intracellular DNA20,21." (PMID 38778121, 2024). "With the growing prominence of targeted therapy in the treatment of advanced or metastatic CRC, the NCCN Panel recommends the determination of tumor gene status for KRAS/NRAS and BRAF mutations." (PMID 39519088, 2024). "Both KRAS mutations and amplifications, as well as NRAS mutations have been identified as mechanisms of resistance to cetuximab and panitumumab both in liquid biopsy and tumor biopsy specimens." (PMID 38711991, 2024). "On the other hand, the serrated-neoplasia pathway is associated with mutations in the oncogenes Neuroblastoma RAS Viral Oncogene Homolog (NRAS) and B-Raf proto-oncogene (BRAF)." (PMID 37507738, 2023). "In contrast, RAS mutant (KRAS, NRAS) tumours (which are more frequent on the left) associate with poor immune infiltration, low inhibitory molecule expression and recruitment of suppressive myeloid cells." (PMID 37251410, 2023). "NRAS mutations are known to drive aggressive tumor growth and pose challenges for current treatments." (PMID 38067230, 2023). "When NRAS-mutated cells become dominant in the tumor, they can reactivate MAPK signaling, circumventing the inhibitory effects of BRAF inhibitors." (PMID 38067230, 2023). "Assessing K- and NRAS mutational status in tumor biopsies is a common procedure in clinical practice, with relevant implications in the choice of the most appropriate pharmacological approach." (PMID 37296579, 2023). "The study included one patient with an NRAS mutation that showed minimal changes in tumor size from the baseline." (PMID 37754515, 2023). "It has been postulated that BRAF and NRAS mutations are most likely due to clonal heterogeneity within the tumor." (PMID 36982192, 2023). "Only one 3’-untranslated region (UTR) insertion variant in the NRAS gene (c.*2010T>AT) was detected in the tumor of the present study, and this was a splice site acceptor." (PMID 37273678, 2023). "In the present study, NRAS mutational status by ctDNA analysis was highly consistent with that observed in tumor tissue." (PMID 36600247, 2023). "To understand the divergence in PIK3CA and NRAS, we analyzed the underlying tumor distributions in our dataset." (PMID 36658200, 2023). "Instead, activating mutations of the CKIT and NRAS genes, low tumor mutation burden, and various gene amplifications or deletions are more commonly observed." (PMID 37898793, 2023). "Overall, these results indicate that miR-708 exclusively exerts its tumor suppressive function on NRAS mutation-driven cancers." (PMID 37083947, 2023). "Mutated or overexpressed NRAS promotes tumor lung colonization by regulating the expression of IL-8-related chemokines and initiating interactions between tumor cells, pulmonary blood vessels, and myeloid cells." (PMID 37511958, 2023).
tumor (continued). "In order to evaluate associations between efficacy and pathologic subtypes and NRAS mutation types, we performed a subgroup analysis among the 15 patients in the 12 mg cohort who have at least one tumor evaluation." (PMID 36600247, 2023). "In contrast, a high-fat diet did not affect the tumor growth rates, masses, sizes, or the body weight in mice with tumor xenografts expressing an active NRAS Q61R mutation." (PMID 35681673, 2022). "As in the case of the NRAS Q61 mutation, the BRAF mutation correlates with tumor invasiveness limited to the submucosa and the right-side colon localization, the latter association being weaker than in the case of NRAS mutations." (PMID 35681771, 2022). "In the previously reported (FV-PTC and FTC with p.(E518K)-mutation) it was also detected NRAS mutations concomitantly; this is in accordance with follicular-patterned tumours where NRAS is frequently found mutated." (PMID 36499151, 2022). "Lethally dependent partners associated with NRAS genetic sequence variants show a p-value histogram that peaks at the origin, meaning that NRAS mutations are associated with more tumor vulnerabilities than other alterations." (PMID 35805023, 2022). "Immune infiltration analysis shows that NRAS is positively correlated with the levels of CD68+ tumor-associated macrophages in HCC samples and that NRAS and CD68 are related to the poor outcome of HCC." (PMID 36348379, 2022). "The NRAS codon 61 mutation was the most frequently detected mutation in both Out-N and PDc tumor areas, accounting for 56.3% of all cases." (PMID 35892838, 2022). "Of note, patients with KRAS/NRAS mutated tumours had numerically superior survival if allocated to the control arm." (PMID 35574322, 2022). "KRAS and NRAS mutation status prevalence was as expected in the first-line setting, as were tumor location and microsatellite stability status." (PMID 36029653, 2022). "To explore the interaction between NRAS alleles in melanocytes, we compared the tumor onset, burden, and overall survival of homozygous (TN61R/R, TN61X/X) and heterozygous (TN61X/R) mice from each of our experimental cohorts." (PMID 35672316, 2022). "One tumor (9%) carried a double NRAS mutation (Q61R and T58A) and one tumor (9%) carried a PIK3CA mutation (E542K)." (PMID 35624529, 2022). "The NRAS type mutations seem to have an impact on tumor localization, with a higher risk towards the right colon." (PMID 35681771, 2022). "For example, secondary KRAS and NRAS mutations in exons 3 and 4 were found to emerge in tumor biopsies and in circulating tumor DNA from patients who progressed to anti-EGFR MoAbs." (PMID 36556139, 2022). "The KRAS G12/G13 mutation was ubiquitous and the NRAS G12/G13 mutation coexisted in the tumor samples we analyzed with the presence of BRAF mutation (AF‰ ≥ 1)." (PMID 35681771, 2022). "Two hallmark features defining cutaneous melanomas are the constitutive activation of the MAPK intracellular cascade, through mutually exclusive gain-of-function mutations in BRAF and NRAS and the high tumor mutational burden (TMB)." (PMID 35409020, 2022). "Of interest, inhibition of USP9X activity by the small-molecule inhibitor DUB G9 also appears to have susceptibility to tumor growth in NRAS mutant lines compared to BRAF lines in vivo and in vitro." (PMID 35884430, 2022). "Tumor tissue biopsy testing is the standard of care to assess RAS (KRAS/NRAS) mutation in these patients." (PMID 36551560, 2022). "Our findings show that KRAS and NRAS mutations especially KRAS mutations have distinct clinicopathological features (tumor site, MSS status, positive lymph node...)." (PMID 33784337, 2021).
tumor (continued). "A novel molecule selectively targeting ERK, SCH772984, induced tumor regression in mouse xenograft models with KRAS or NRAS mutations." (PMID 34301278, 2021). "It is unclear if NRAS has any prognostic value if identified, but NRAS expression is associated with higher tumour staging and lower grades of tumour infiltrating lymphocytes." (PMID 34441278, 2021). "Tumors with NRAS mutation are reported to have low tumor-infiltrating lymphocyte (TIL) grades, suggesting a more immunosuppressive microenvironment." (PMID 34290710, 2021). "Somatic mutations of BRAF and NRAS result in the hyperactivation of mitogen-activated protein kinase (MAPK) signaling that drives tumor growth and leads to progression of the disease." (PMID 34209415, 2021). "When oncogenic NRAS was detected in PAX3-FOXO1-positive aRMS tumor tissue, it was accompanied by loss of heterozygosity of chromosome 11p58." (PMID 34389744, 2021). "The mutation frequency in synopsis with the tumor cell content revealed the presence of the NRAS mutation on one allele, excluding subclonal events." (PMID 34072863, 2021). "The effects of NRAS/BRAF mutation on the tumor microenvironment need to be evaluated in future studies using larger cohorts." (PMID 34272423, 2021). "NRAS mutations were identified in 14 (28%) tumours and were all in hotspot positions on exons 2 (codons 12 and 13) and 3 (codon 61) and mutually exclusive from BRAFV600 mutations." (PMID 33024263, 2021). "Significant associations of the studied SNPs with clinicopathologic variables were also observed between NRAS rs14804 minor T allele and advanced tumor stage and positive lymph node status." (PMID 34828284, 2021). "KRAS and NRAS mutation were detected in 39.5% (83/210) of tumor cases examined, of which 36.7% (77/210) and 2.9% (6/210) were occurred in KRAS and NRAS gene respectively." (PMID 33784337, 2021). "Characterization of these neoplasms has shown a high prevalence of NRAS mutations that additionally drive the MAPK-pathway." (PMID 33921947, 2021). "Patients whose tumor harbored NRAS mutations or that coexpressed also BRAF mutations were excluded from this retrospective analysis." (PMID 34660299, 2021). "BRAF and NRAS mutations were found to be independent prognostic factors of poor OS in our cohort of CRC patients with tumor recurrence." (PMID 33919924, 2021). "BRAF or NRAS mutations previously identified in tumour tissues were found in 34 out of 68 patients, representing an overall 50% sensitivity between tissue analyses and circulating DNA analysis on the Cobas system." (PMID 32664549, 2020). "In summary, the molecular analysis of a small amount of unamplified cfDNA for BRAF, KRAS and NRAS mutations in MM patients is feasible and has good concordance with standard mutations testing of bone marrow tumor DNA samples." (PMID 32284750, 2020). "Positive NRAS expression was also associated with a lower grade of tumor-infiltrating lymphocytes and a higher tumor stage." (PMID 32429485, 2020). "In the immunotherapy cohort, 30 patients were BRAF mutant (42%), 20 were NRAS mutant (28%) and 22 patients had other driver mutations that were used to track the tumour." (PMID 33339135, 2020). "On the contrary, NRAS mutation was significantly associated with ulcerative (p = 0.043) and well/moderately-differentiated tumor (p = 0.040)." (PMID 32161617, 2020).